C1orf162 (chromosome 1 open reading frame 162)
Synonyms: MGC24133
Tractability: Antibody: UniProt predicts a signal peptide or a membrane-spanning region.
Gene: Protein-coding gene on chromosome 1 (111,473,792 to 111,478,512, forward strand). Ensembl gene ENSG00000143110.
Subcellular location: Membrane
Subcellular location (Human Protein Atlas): Golgi apparatus; Nucleoplasm
Gene Ontology:
Cellular component: membrane
Genetic constraint (gnomAD): Loss-of-function variants: 11 observed, 12.65 expected, observed/expected ratio (o/e) 0.87, 90% interval 0.55 to 1.43. The upper end of that interval is the gene's LOEUF score, 1.43, which puts it in group 5 of 6, group 1 being the genes least tolerant of losing a copy. Missense variants: 138 observed, 156.11 expected, observed/expected ratio (o/e) 0.88, 90% interval 0.77 to 1.02. Synonymous variants: 52 observed, 58.14 expected, observed/expected ratio (o/e) 0.89, 90% interval 0.71 to 1.13.
Homologues: Orthologues: chimpanzee C1H1orf162 (100% identical), macaque C1H1orf162 (88% identical), rabbit C1orf162 (65% identical), guinea pig C1orf162 (60% identical), mouse I830077J02Rik (55% identical), rat C2h1orf162 (55% identical), dog C17H1orf162 (55% identical).
Diseases named in the same sentence as C1orf162 in open-access papers:
C1orf162 is named in the same sentence as 9 diseases in open-access papers, as found by Europe PMC text mining. Sharing a sentence is not in itself a finding about the gene and the disease. The quoted sentences say what the papers report.
breast carcinoma (1 paper, 2024). "In previous bioinformatic studies, C1orf162 was identified as a signature gene related to co-occurrence of heart failure, lung cancer, polycystic ovary syndrome, and breast cancer." (PMID 39296904, 2024).
metastatic tumors (1 paper, 2023). "In general, overexpression of the C4orf46, C9orf40, C17orf67 and C21orf58 gene of thymoma correlates with tumor immune cell infiltration and gene expression levels of C1orf162, C16orf54 and CXorf21 correlate with immune cell infiltration in many primary and metastatic tumors." (PMID 37373333, 2023).
Obesity (1 paper, 2024). Accumulation of substantial excess body fat. "The expression of PTX3, NCF2, HOXB5, ABCA6, and C1orf162 were upregulated in the placenta of mothers with obesity compared with mothers with normal BMI." (PMID 39296904, 2024).
C1orf162 also shares sentences with these, for which no sentence is quoted: tumor (2 papers); cancer (1); heart failure (1); lung carcinoma (1); polycystic ovary syndrome (1); thymoma (1).